SSTR1 (somatostatin receptor 1)
Diseases named in the same sentence as SSTR1 in open-access papers (continued):
Sharing a sentence is not in itself a finding about the gene and the disease.
somatotropinomas (3 papers, 2018 to 2024). "Although SSTR1 mRNA expression levels were relatively low in somatotropinomas, we observed that SSTR1 expression was higher in patients who responded better to SSAs." (PMID 29266696, 2018). "In conclusion, the systematic evaluation of DRD and SSTR expression in somatotropinomas has revealed an association between the response to SSAs treatment and DRD4, DRD5, SSTR1 and SSTR2 expression." (PMID 29266696, 2018). "Furthermore, in vitro studies have revealed that SSTR1 agonists can inhibit GH secretion in somatotropinomas." (PMID 29266696, 2018). "Somatostatin receptor subtype 5 mRNA was highest in somatotropinomas, followed by SSTR2 > SSTR3 >> SSTR1 >>> SSTR4." (PMID 39202532, 2024). "In somatotropinomas, SSTR5 was the predominant SSTR subtype detected, followed by SSTR2, SSTR3 and SSTR1." (PMID 29266696, 2018). "It has been suggested that the differential efficacy of somatostatin analogs in the postoperative treatment of somatotropinomas and NFPA may be partly due to the differential expression of SSTR1-5 within and between pituitary tumor types." (PMID 39202532, 2024). "Altogether, these results suggest that SSTR1 could also play a role in the regulation of GH secretion in pituitary tumours and, therefore, that the potential role of this SSTR in somatotropinomas deserves further study." (PMID 29266696, 2018).
glioma (2 papers, 2023 to 2024). A benign or malignant brain and spinal cord tumor that arises from glial cells (astrocytes, oligodendrocytes, ependymal cells). "Among different cancer types in TCGA, SSTR1 mRNA in primary PCa is higher than all the other cancer types except glioma." (PMID 39352383, 2024).
head and neck squamous cell carcinoma (2 papers, 2015 to 2018). A squamous cell carcinoma that arises from any of the following anatomic sites: lip and oral cavity, nasal cavity, paranasal sinuses, pharynx, larynx, and salivary glands. "Finally, the SST1 gene promoter contains two CpG islands, putatively involved in head and neck squamous cell carcinoma tumorigenesis, where hypermethylation of the SSTR1, but also of SRIF, gene has been correlated with reduced disease-free survival." (PMID 30232095, 2018). "The aim of this study was to define somatostatin (SST) and somatostatin receptor type 1 (SSTR1) methylation profiles for head and neck squamous cell carcinoma (HNSCC) tumors at diagnosis and follow up and to evaluate their prognostic significance and value as a biomarker." (PMID 25734919, 2015).
Hyperinsulinemia (2 papers, 2012 to 2025). An increased concentration of insulin in the blood. "Interestingly, during the investigation of the SSTR1 inhibition of the growth hormone mechanism, it was observed that hyperinsulinemia was induced after knocking out the SSTR1 gene in mice, which is indeed one of the pathogenic mechanisms of NAFLD." (PMID 39619480, 2025).
pancreatic cancer (2 papers, 2020 to 2023). "In vitro and in vivo studies suggest that SSTR1, SSTR2, and SSTR5 suppress the growth of pancreatic cancer." (PMID 37900156, 2023).
pituitary adenomas (2 papers, 2018 to 2019). "Previous reports of SSTR mRNA expression in GH-secreting pituitary adenomas in humans describe SSTR5 > SSTR2 whereas SSTR1 and SSTR3 expression can be highly variable and SSTR4 expression is absent." (PMID 30620005, 2019). "Tissue samples of 236 pituitary adenomas were available for microscopic evaluation of SSTR1 expression." (PMID 30627156, 2018). "We proclaim the need to assess the expression of SSTR1-5 on a routine basis in corticotroph pituitary adenomas to allow individual treatment decisions and to gain experience about receptor dynamics during treatment." (PMID 30627156, 2018). "Since immunohistochemistry of SSTR1-5 is known to show homogenous staining in pituitary adenomas, this does probably not have a significant impact." (PMID 30627156, 2018).
prolactinomas (2 papers, 2022 to 2025). "Somatostatin receptor (SSTR) expression in prolactinomas is very variable with a predominance of SSTR5, followed by SSTR2A and SSTR1." (PMID 35683457, 2022).
schizophrenia (2 papers, 2014 to 2021). A major psychotic disorder characterized by abnormalities in the perception or expression of reality. "For example Beneyto and co-workers used in situ hybridization to quantify the mRNA expression levels of SST receptors subtype 1 (SSTR1) and subtype 2 (SSTR2) in dorsolateral prefrontal cortex area 9 from 23 matched pairs of subjects with schizophrenia and normal comparison subjects." (PMID 24570674, 2014).
adrenal tumors (1 paper, 2023). "Mariniello implied that SSTR1 and SSTR2 mRNA was expressed in 100% of adrenal tumors." (PMID 37185426, 2023).
Arthritis (1 paper, 2022). Inflammation of a joint. "The role of SSTR1 in RA and OA has not yet been studied and the present results may provide a basis for future study on arthritis." (PMID 35602512, 2022).
B-cell NHL (1 paper, 2021). "Recently, one pediatric HL case was reported to co-express mRNA for all five SSTR subtypes (SSTR1-5) and in a small cohort of aggressive nasopharyngeal B-cell NHL, 40% of the 15 cases were SSTR2 positive." (PMID 34307181, 2021).
carcinoid syndrome (1 paper, 2024). "Given their antitumor effects, somatostatin analogs such as octreotide and lanreotide (both are potent SSTR2 agonists but notably spare SSTR1) have been approved to treat gastroenteropancreatic NE tumors and carcinoid syndrome." (PMID 39352383, 2024).
cardiomyopathy (1 paper, 2024). A disease of the heart muscle or myocardium proper. "We showed, in a small cohort of ICM patients, that SSTR1 tends to be upregulated at the expression and protein level in end-stage cardiomyopathy myocardium with ongoing cardiac remodeling and stress and present fibrotic scar but without overly active pro-fibrotic remodeling." (PMID 39038008, 2024).
Chordoid Meningioma (1 paper, 2022). A WHO grade II, usually recurring meningioma characterized by the predominance of tissues that are histologically similar to chordoma. "Among WHO grade II tumors, chordoid meningiomas had higher expression scores for SSTR1 and 2A compared to atypical meningiomas." (PMID 33899156, 2022).
corticotroph adenomas (1 paper, 2018). "In this study, we analyzed the immunohistochemical expression of SSTR1-5 in the largest group of corticotroph adenomas so far." (PMID 30627156, 2018). "Recurrent CD cases showed a significantly higher expression of SSTR1 (p = 0.0351) and SSTR4 (p = 0.0174) while SSTR5 ID scores were lower than in primary corticotroph adenomas (p = 0.0370)." (PMID 30627156, 2018). "Inactive adenomas showed the highest rate of SSTR1 expression above the cut-off (20%, 16/81), followed by gonadotroph (14%, 3/22), PIT-1-positive (13%, 7/54), and corticotroph adenomas (9%, 7/79)." (PMID 30627156, 2018). "While SSTR2 and SSTR4 were not detectable in corticotroph adenomas, one out of three cases showed expression of SSTR1 and one out of two for SSTR3 and SSTR5." (PMID 30627156, 2018).
diabetes (1 paper, 2021). "The expression patterns of SSTRs in islet cells are altered in type 2 diabetes mellitus (T2DM), with diminished levels of SSTR1 and SSTR4 in α-cells and SSTR1-4 in δ-cells, which could further contribute to impaired somatostatin paracrine regulation in diabetes." (PMID 33494193, 2021).
Dyskinesia (1 paper, 2022). A movement disorder which consists of effects including diminished voluntary movements and the presence of involuntary movements. "Notably, in a MPTP-induced PD mouse model, overexpressed HOTAIR stimulated DNA methylation of SSTR1 to reduce SSTR1 expression, thereby accelerating dyskinesia and facilitating dopaminergic neuron apoptosis." (PMID 35813070, 2022).
hematoma (1 paper, 2018). A hematoma is a collection of blood from a vascular structure into an extravascular space. "Furthermore, SSTR1 co-localized with active-caspase-3 and bcl-2 around the hematoma, while the expression of active-caspase-3 was parallel with that of SSTR1 in a time-dependent manner, indicating that up-regulated SSTR1 contributed to neuronal apoptosis following ICH." (PMID 29522573, 2018).
intracerebral hemorrhage (1 paper, 2018). A cerebrovascular disorder characterized by bleeding into one or both cerebral hemispheres including the basal ganglia and the cerebral cortex. "In addition, it has been shown that SSTR1 is upregulated in a rat intracerebral hemorrhage (ICH) model, whereas the SSTR1 protein was mostly co-localized with neurons, and was rarely distributed in activated astrocytes and microglia." (PMID 29522573, 2018).
ischemia (1 paper, 2021). A hypoperfusion of the BLOOD through an organ or tissue caused by a PATHOLOGIC CONSTRICTION or obstruction of its BLOOD VESSELS, or an absence of BLOOD CIRCULATION. "The relative expression of SSTR1 was significantly upregulated in the remote ischemic conditioning group compared to the ischemia/reperfusion group." (PMID 34803662, 2021).
keratoconus (1 paper, 2009). A degenerative, structural disorder of the eye, characterized by a cone-shaped protrusion of the cornea. "We found that SSTR1 expression was downregulated in keratoconus." (PMID 19956410, 2009). "However, we assessed the expression of eight genes in more detail by employing RT-PCR and real-time PCR, which confirmed the overexpression of BMP4, CFL1, and MRVI1, and the underexpression of ACTA2, GRCC10, TIMP3, TIMP1, and SSTR1 in keratoconus." (PMID 19956410, 2009).
kidney cancer (1 paper, 2021). Primary or metastatic malignant neoplasm involving the kidney. "In addition, we performed qRT-PCR analysis on clinical specimens and found that the mRNA expression levels of FGF17, PRKCG, and SSTR1 were significantly different between kidney cancer tissues and normal tissues adjacent to the cancer." (PMID 35155566, 2021).
laryngeal carcinoma (1 paper, 2016). Carcinoma that arises from the laryngeal epithelium. "Previous laryngeal cancer study has shown that the overall pattern of SSTRs expression is with high levels of SSTR1, “loss” of SSTR2 and intermediate levels of SSTR5." (PMID 26796520, 2016).
neurofibroma (1 paper, 2021). An intraneural or extraneural neoplasm arising from nerve tissues and neural sheaths. "SSTR1 and SSTR5 presented the same immunoreactivity, as one case of neurofibroma and one case of schwannoma were negative and the other tumor samples were positive." (PMID 34830858, 2021).
oral cancer (1 paper, 2018). "In patients with oral cancer, the methylation of TAC1 and SSTR1 best correlated with poor survival (hazard ratio: 4.29; p = 0.005 and 5.38; p = 0.029, respectively)." (PMID 29361757, 2018).
oropharynx cancer (1 paper, 2015). A primary or metastatic malignant neoplasm that affects the oropharynx. "Among patients with oral cavity and oropharynx cancer, methylation of both SST and SSTR1 promoters correlated with reduced disease-free survival (log-rank test, P = 0.028)." (PMID 25734919, 2015). "Among patients with oral cavity and oropharynx cancer, the disease-free survival rate in the group of patients with both SST and SSTR1 methylation was 48.1% as compared with 81.4% in the other groups (log-rank test, P = 0.028)." (PMID 25734919, 2015).
osteomalacia (1 paper, 2016). Disorder caused by an interruption of the mineralization of organic bone matrix leading to bone softening, bone pain, and weakness. "Tumors associated with osteomalacia variably express somatostatin receptors (SSTR1–5), allowing SSTR-based functional imaging by octreotide scintigraphy such as 111In-pentetreotide." (PMID 27709474, 2016).
pancreatic adenocarcinoma (1 paper, 2018). "It is reported that gene transfer using somatostatin receptor 1 (SSTR1) inhibits the growth of pancreatic adenocarcinoma through cell cycle arrest in vivo and in vitro." (PMID 29596435, 2018). "Our study found that SSTR1 was expressed in all grades of tumor differentiation of pancreatic adenocarcinoma, which further demonstrated the crucial role of SSTR1 in the development of pancreatic adenocarcinoma." (PMID 29596435, 2018).
pituitary (1 paper, 2016). "Our results show that pasireotide, a multireceptor-targeted SA with high affinity for SSTR1, 2, 3, and 5 is effective in reducing proliferation and increasing apoptosis of pancreatic and pituitary NETs that develop in a mouse model for MEN1." (PMID 26990064, 2016).
renal carcinoma (1 paper, 2021). A carcinoma arising from the epithelium of the renal parenchyma or the renal pelvis. "Interestingly, the gene probes targeting FGF17, PRKCG, SSTR1, and SCTR predicted potential targeted agents for renal cancer metastasis and adjuvant immunotherapy, including 5224221, calmidazolium, and sulfasalazine." (PMID 35155566, 2021).
renal cell carcinoma (1 paper, 2023). "One preliminary study confirmed that SSTR1 is a target gene affecting renal cell carcinoma (RCC) metastasis and the associated immune response and could be a prognostic biological marker of and viable therapeutic target for RCC." (PMID 37900156, 2023).
small cell lung carcinoma (1 paper, 2017). Small cell lung cancer (SCLC) is a highly aggressive malignant neoplasm, accounting for 10-15% of lung cancer cases, characterized byrapid growth, and early metastasis. "The small cell lung cancer cell line NCI-H69 was devoid of SSTR1 expression but strongly expressed SSTR2, SSTR3, and SSTR5." (PMID 29282035, 2017).
Telangiectasia (1 paper, 2023). Telangiectasias refer to small dilated blood vessels located near the surface of the skin or mucous membranes, measuring between 0.5 and 1 millimeter in diameter. "Significant expression changes existed also for genes responsible for the pathogenesis of telangiectasia (upregulation of Sst, Sstr1, Sstr2, Tac1, Tacr1, Svbp), and for general growth (Sst, Sstr1, Sstr2)." (PMID 37830614, 2023).
tumor (49 papers, 1997 to 2025). "We tested the association between SSTR1 mRNA and the burden of functional protein-coding mutations in each gene, using a linear regression model adjusting for tumor purity." (PMID 39352383, 2024). "SSTR1 was linked to androgen receptor (AR) expression and tumor metastasis." (PMID 33995646, 2021). "Conversely, recurrent-tumours (more aggressive than primary-tumours) showed higher SSTR1 and/or SSTR2 levels." (PMID 40268793, 2025). "A lower SSTR1 and SSTR2 expression levels was associated to primary tumours compared to recurrent GBMs in the TCGA/Murat-cohorts." (PMID 40268793, 2025). "We provide preliminary data to support tumor SSTR1 expression as a promising candidate for such a biomarker." (PMID 39352383, 2024). "Reduced expression of eight immune‐related genes (IRGs) (NT5E, THRA, RBP1, TLR4, ITGA6, BMPR1B, ITGAV, SSTR1) in tumor strongly predicted better quality of prognosis, both in our patient cohort and in TCGA‐HNSC cohort." (PMID 37392167, 2023). "Its activity is mediated by five distinct SST receptor subtypes (SSTR1–5), and it inhibits the release of hormones as well as the growth of tumours." (PMID 36986832, 2023). "Several previous studies have demonstrated the expression of SSTR1 subtypes in control and tumor colon tissues at the level of protein and mRNA with a distinct pattern of distribution." (PMID 38203605, 2023). "In total, five SSTR subtypes (SSTR1, 2, 3, 4, and 5) have been identified and shown to be expressed in numerous healthy tissues and tumours." (PMID 36362289, 2022). "Spinal meningiomas had higher scores for SSTR1, 4, and 5 compared tumor location of the skull base and convexity/falx." (PMID 33899156, 2022). "Overall, 726 tumor samples were processed into tissue microarrays and stained for SSTR1, 2A, 3, 4, and 5 immunohistochemically." (PMID 33899156, 2022). "Immunohistochemical (IHC) staining for SSTR1–5, and Ki67 were carried out for tumor xenografts from the three cell lines." (PMID 34433438, 2021). "Tumor tissue from respective NB cell line derived xenografts were stained for expression of SSTR1–5 and Ki67." (PMID 34433438, 2021). "Differences related to tumor grade were evident for SSTR1 (p = 0.036), SSTR2 (p = 0.009) and SSTR5 (p = 0.029), while differences for SSTR3 (p = 0.059) were non-significant." (PMID 34830858, 2021). "There are reports on the immunohistochemical (IHC) profile of SSTR1-5 in PNENs, but, to our knowledge, few published studies have analyzed all five human SSTRs of the tumor and their correlations with molecular imaging using PET/CT." (PMID 35008325, 2021). "Clinical data of patients were collected, and complex immunohistochemical assessment of tumour samples was performed (SSTR1‐5, dopamine D2 receptor, E‐cadherin, AIP)." (PMID 33491286, 2021). "FGF17, PRKCG, and SSTR1 were detected with the same results in tumor tissues and adjacent normal kidney tissues, while SCTR was not significantly different." (PMID 35155566, 2021). "Comparing relative receptor expression intensities between the two tumor entities, CCCs showed significantly higher intensities of expression of SSTR1, SSTR2, SSTR5, and CXCR4 than HCCs." (PMID 29282035, 2017). "That SST and SSTR1 were always expressed in the normal colonic epithelial cells, and SST was completely lost in the tumor cells while SSTR1 was also expressed in the tumor cells of some patients is an important finding." (PMID 27927191, 2016). "SSTR1 hypermethylation in 64% of cases was correlated with tumor size (P = 0.037), stage (P = 0.037), SST methylation (P < 0.001), and expression of galanin (P = 0.03), GALR2 (P = 0.014), TAC1 (P = 0.023), and tachykinin receptor type 1 (TACR1) (P = 0.003)." (PMID 25734919, 2015). "Our study highlights the heterogeneity of the G3 neoplasms, and describes significant differences in SSTR1 and CXCR4 expression." (PMID 26259237, 2015).